WNK1 (WNK lysine deficient protein kinase 1)
Description:
Serine/threonine-protein kinase component of the WNK1-SPAK/OSR1 kinase cascade, which acts as a key regulator of blood pressure and regulatory volume increase by promoting ion influx. WNK1 mediates regulatory volume increase in response to hyperosmotic stress by acting as a molecular crowding sensor, which senses cell shrinkage and mediates formation of a membraneless compartment by undergoing liquid-liquid phase separation. The membraneless compartment concentrates WNK1 with its substrates, OXSR1/OSR1 and STK39/SPAK, promoting WNK1-dependent phosphorylation and activation of downstream kinases OXSR1/OSR1 and STK39/SPAK. Following activation, OXSR1/OSR1 and STK39/SPAK catalyze phosphorylation of ion cotransporters SLC12A1/NKCC2, SLC12A2/NKCC1, SLC12A5/KCC2 and SLC12A6/KCC3, regulating their activity. Phosphorylation of Na-K-Cl cotransporters SLC12A2/NKCC1 and SLC12A2/NKCC1 promote their activation and ion influx; simultaneously, phosphorylation of K-Cl cotransporters SLC12A5/KCC2 and SLC12A6/KCC3 inhibit their activity, blocking ion efflux. Also acts as a regulator of angiogenesis in endothelial cells via activation of OXSR1/OSR1 and STK39/SPAK: activation of OXSR1/OSR1 regulates chemotaxis and invasion, while STK39/SPAK regulates endothelial cell proliferation. Also acts independently of the WNK1-SPAK/OSR1 kinase cascade by catalyzing phosphorylation of other substrates, such as SYT2, PCF11 and NEDD4L. Mediates phosphorylation of SYT2, regulating SYT2 association with phospholipids and membrane-binding (By similarity). Regulates mRNA export in the nucleus by mediating phosphorylation of PCF11, thereby decreasing the association between PCF11 and POLR2A/RNA polymerase II and promoting mRNA export to the cytoplasm. Acts as a negative regulator of autophagy. Required for the abscission step during mitosis, independently of the WNK1-SPAK/OSR1 kinase cascade. May also play a role in actin cytoskeletal reorganization. Also acts as a scaffold protein independently of its protein kinase activity: negatively regulates cell membrane localization of various transporters and channels, such as SLC4A4, SLC26A6, SLC26A9, TRPV4 and CFTR (By similarity). Involved in the regulation of epithelial Na(+) channel (ENaC) by promoting activation of SGK1 in a kinase-independent manner: probably acts as a scaffold protein that promotes the recruitment of SGK1 to the mTORC2 complex in response to chloride, leading to mTORC2-dependent phosphorylation and activation of SGK1. Acts as an assembly factor for the ER membrane protein complex independently of its protein kinase activity: associates with EMC2 in the cytoplasm via its amphipathic alpha-helix, and prevents EMC2 ubiquitination and subsequent degradation, thereby promoting EMC2 stabilization. [Isoform 3]: Kinase-defective isoform specifically expressed in kidney, which acts as a dominant-negative regulator of the longer isoform 1. Does not directly inhibit WNK4 and has no direct effect on sodium and chloride ion transport (By similarity). Down-regulates sodium-chloride cotransporter activity indirectly by inhibiting isoform 1, it associates with isoform 1 and attenuates its kinase activity (By similarity). In kidney, may play an important role regulating sodium and potassium balance (By similarity).
Synonyms: p65; HSN2; KDP; PRKWNK1; HSAN2; PPP1R167; PSK
Tractability: Small molecule: a structure with a bound ligand is known; a high-quality ligand is known; it belongs to a druggable protein family. PROTAC: UniProt records ubiquitination sites on it; ubiquitination databases record sites on it; its protein half-life has been measured; a small molecule that binds it is known.
Target class: Kinase; Enzyme; Protein Kinase; Other protein kinase Wnk family; Other protein kinase group
Gene: Protein-coding gene on chromosome 12 (752,536 to 911,452, forward strand). Ensembl gene ENSG00000060237.
Subcellular location: Cytoplasm; Nucleus; Cytoplasm, cytoskeleton, spindle
Subcellular location (Human Protein Atlas): Cytosol
Pathways (Reactome):
Transport of small molecules: Stimuli-sensing channels
Gene Ontology:
Molecular function: ATP binding; molecular condensate scaffold activity; phosphatase binding; protein binding; protein kinase activator activity; protein kinase activity; protein kinase binding; protein serine kinase activity; protein serine/threonine kinase activity
Biological process: cell volume homeostasis; cellular hyperosmotic response; cellular response to chemokine; intracellular signal transduction; membraneless organelle assembly; negative regulation of autophagy; negative regulation of cell-cell adhesion mediated by integrin; negative regulation of heterotypic cell-cell adhesion; negative regulation of leukocyte cell-cell adhesion; negative regulation of protein ubiquitination; negative regulation of small GTPase mediated signal transduction; positive regulation of angiogenesis; positive regulation of canonical Wnt signaling pathway; positive regulation of mitotic cytokinesis; positive regulation of T cell chemotaxis; positive regulation of termination of RNA polymerase II transcription; protein insertion into ER membrane by stop-transfer membrane-anchor sequence; protein phosphorylation; regulation of monoatomic cation transmembrane transport; regulation of mRNA export from nucleus; signal transduction; chemokine (C-C motif) ligand 21 signaling pathway; DNA damage response; lymphocyte migration into lymph node; monoatomic cation homeostasis; and 12 more
Cellular component: cytoplasm; cytosol; intracellular membraneless organelle; mitotic spindle; nucleus; membrane; spindle
Genetic constraint (gnomAD): Loss-of-function variants: 37 observed, 214.35 expected, observed/expected ratio (o/e) 0.17, 90% interval 0.13 to 0.23. The upper end of that interval is the gene's LOEUF score, 0.23, which puts it in group 1 of 6, group 1 being the genes least tolerant of losing a copy. Missense variants: 2,278 observed, 2,975.6 expected, observed/expected ratio (o/e) 0.77, 90% interval 0.74 to 0.79. Synonymous variants: 1,065 observed, 1,120.5 expected, observed/expected ratio (o/e) 0.95, 90% interval 0.9 to 1.
Gene-disease validity (ClinGen):
ClinGen rates the evidence that WNK1 causes each of these diseases.
neuropathy, hereditary sensory and autonomic, type 2A (autosomal recessive): Definitive.
Homologues: Orthologues: chimpanzee WNK1 (99% identical), macaque WNK1 (97% identical), rabbit WNK1 (91% identical), rat Wnk1 (86% identical), pig WNK1 (86% identical), dog WNK1 (86% identical), mouse Wnk1 (80% identical), guinea pig WNK1 (78% identical), tropical clawed frog wnk1 (54% identical), zebrafish wnk1b (43% identical), zebrafish wnk1a (33% identical), Drosophila melanogaster Wnk (22% identical), and 3 more. Paralogues in human: WNK2 (29% identical), WNK3 (26% identical), WNK4 (21% identical), DSTYK (7% identical), NRBP1 (6% identical), NRBP2 (6% identical).
Diseases named in the same sentence as WNK1 in open-access papers:
WNK1 is named in the same sentence as 133 diseases in open-access papers, as found by Europe PMC text mining. Sharing a sentence is not in itself a finding about the gene and the disease. The quoted sentences say what the papers report.
Hypertension (53 papers, 2009 to 2025). The presence of chronic increased pressure in the systemic arterial system. "A significant association was observed between the rs880054 variant of the WNK1 gene and hypertension susceptibility, with the T allele elevating the risk of hypertension." (PMID 39859138, 2025). "Fifth, considering low statistical power for several SNVs in our study, caution should be exercised when extrapolating the insignificant association between the SNV for WNK1 and hypertension." (PMID 37779914, 2023). "Significant associations were observed between WNK1 gene rs7305099 variant and EH risk, and T allele influenced hypertension risk in a protective manner." (PMID 37779914, 2023). "Hypertension linked to WNK1 appears to be uniquely responsive to thiazide diuretics due to the associated electrolyte transport abnormalities." (PMID 37965396, 2023). "Rs956868 is located on the exon 13 of the WNK1 gene, and its association with the genetic susceptibility to hypertension has been reported in various ethnic groups." (PMID 37779914, 2023). "The SNV rs1468326, located 3 kb from the WNK1 promoter, was first found to be associated with severity of hypertension in families from the British Genetics of Hypertension (BRIGHT) Study in 2005." (PMID 37779914, 2023). "WNK1: Abnormalities in the expression of WNK Lysine Deficient Protein Kinase 1 (WNK1) can lead to monogenic hypertension through their effects on renal electrolyte transport." (PMID 37965396, 2023). "The best-studied variant of WNKs for hypertension is the kidney-specific WNK1 (KS-WNK1), a variant of full-length WNK1 (L-WNK1)." (PMID 36305246, 2022). "The with-no-lysine (WNK) kinase family, comprising four serine-threonine protein kinases (WNK1-4), were first linked to hypertension due to their mutations in association with pseudohypoaldosteronism type II (PHAII)." (PMID 36140271, 2022). "Of the genes overexpressed in patients before or after HCT, WNK1 is associated with a monogenic type of hypertension, while BAT2D1, MOV10, PIK3CG are genetic variants associated with BP5,25." (PMID 33927307, 2021). "WNK1 was initially shown to regulate the activity of a variety of renal ion channels because WNK1 gene mutations cause a rare familial form of hypertension." (PMID 33315986, 2020). "WNK1 causes hypertension and hyperkalemia when overexpressed in the kidneys and embryonically lethal cardiovascular defects when homozygously deleted in animals." (PMID 29904119, 2018). "Overexpression of WNK1 has also been linked to hypertension and hyperkalemia through alterations in sodium and potassium handling." (PMID 28178938, 2017). "Mutations in WNK1 have been discovered in a number of diseases, such as hypertension, pseudohypoaldosteronism type 2 (MIM 145260), and hereditary sensory neuropathy type 2." (PMID 25739019, 2015). "Mutations in WNK1 were discovered to cause a familial form of hypertension known as Gordon's syndrome, characterized by increased renal salt reabsorption." (PMID 24945252, 2014). "Overexpression of WNK1 causes hypertension and hyperkalemia in humans by altering renal Na+ and K+ transport." (PMID 25171174, 2014). "WNK1 causes hypertension and hyperkalemia when overexpressed and cardiovascular defects when ablated in mice." (PMID 25171174, 2014). "Deletion in intron 1 of WNK1 gene in PHAII patients caused the increased expression of WNK1, which leads to hypertension by the misregulation of ion cotransporters." (PMID 23517227, 2013). "The design of the current study did not allow us to draw any conclusion about the contribution of the WNK1 AluYb8 insertion to the risk for developing hypertension." (PMID 21520334, 2011). "We targeted conserved noncoding regions in hypertension candidate genes WNK1 and WNK4 to polymorphism screening in order to identify functional variants potentially contributing to BP determination." (PMID 21520334, 2011).
Hypertension (continued). "Our data indicates that multiple rare and common WNK1 variants contribute to BP variation and hypertension, and provide compelling evidence to initiate further genetic and functional studies to explore the role of WNK1 in BP regulation and EH." (PMID 19347040, 2009). "Therefore, further research is required to identify specific regions of the WNK1 gene that harbor functional genetic variations associated with hypertension (HTN) and medication response." (PMID 39859138, 2025). "Additionally, consistent result was found that the SNV rs1468326 associated with EH for Tibetan individuals in China, which supports the role of WNK1 as potential hypertension susceptibility genes." (PMID 37779914, 2023). "Blunted ADRB2 and WNK1 function have been implicated in the pathogenesis of hypertension." (PMID 33316892, 2020). "Accordingly, several mutations resulted in WNK1 over-expression have been reported as the causative mutations of an autosomal dominant disorder, pseudohypoaldosteronism type II, which is characterized by hypertension, hyperkalemia, and renal tubular acidosis." (PMID 30497409, 2018). "Ashyperactive WNK1 is known to cause high blood pressure, the control of WNK1 protein abundance byubiquitylation through CUL3–KLHL3 may be critical for blood pressure control." (PMID 23387299, 2013). "WNK1 polymorphisms have also been associated with common essential hypertension." (PMID 23285140, 2012). "In PHA2 patients, gain-of-expression mutations in WNK1 cause hypertension." (PMID 19347040, 2009). "More subtle mutations, however, that lead to decreased WNK1 expression or function may be ‘protective’ against hypertension, and preserved at low frequencies in the general population." (PMID 19347040, 2009). "Moreover, mutations in WNK1 can lead to dysregulated ion transport in vascular smooth muscle cells, which may cause abnormal vasoconstriction or vasodilation, contributing to hypertension." (PMID 40894397, 2025). "Data obtained from this study have shown that the rs7305099 variant in the WNK1 gene was significantly related to EH risk in the Northern Han Chinese population after Bonferroni correction for multiple testing, and T allele was a protective factor for hypertension." (PMID 37779914, 2023). "Finally, our study suggests clinical implications of inhibiting the WNK1 pathway, including the use of diuretics to treat high blood pressure, as inflammatory complications linked to NLRP3 regulation by the WNK1 pathway may arise." (PMID 34315884, 2021). "Therefore, there is an association between WNK1 and severe hypertension." (PMID 27765018, 2016). "This study provides new insights into the genetic factors contributing to hypertension and highlights the potential of WNK1 as a target for future therapeutic interventions." (PMID 39859138, 2025). "Mutations in WNK1 result in dysregulation of the WNK1-SPAK/OSR1 pathway and cause pseudohypoaldosteronism type II (PHAII), a form of hypertension." (PMID 36151370, 2022). "Initial attention was focused on these enzymes as regulators of blood pressure because mutations of two family members, WNK1 and WNK4, caused pseudohypoaldosteronism type II, a heritable form of hypertension." (PMID 36212467, 2022). "Mutations of WNK1 and WNK4 cause Gordon syndrome (pseudohypoaldosteronism type 2, PHA 2) accompanied by hypertension, elevated serum potassium, and acidosis." (PMID 36305246, 2022). "WNK1 is a newly discovered ion channel regulatory protein, and its effect on hypertension is being investigated." (PMID 33503173, 2021). "Our results revealed that the expression of LRRC8A was progressively increased during the development of hypertension, accompanied by the activation of WNK1." (PMID 34725866, 2021). "Hypertension and hyperkalemia in pseudohypoaldosteronism type-2 (PHA2) patients with WNK1 and WNK4 mutations lead to the understanding of roles of WNK kinases in ion homeostasis." (PMID 32131390, 2020).
Hypertension (continued). "Mutations in WNK1 and WNK4 genes caused a Mendelian form of hypertension, Familial Hyperkalemic Hypertension (FHHt) also known as pseudohypoaldosteronism type 2 or Gordon’s syndrome." (PMID 33066544, 2020). "Gain-of-function mutations of WNK1 and WNK4 cause a mendelian hypertension and hyperkalemic disease." (PMID 32131390, 2020). "Gain-of-function of WNK1 and WNK4 caused by gene mutation leads to an autosomal-dominant disease pseudohypoaldosteronism type 2 (PHA2) featured by hypertension, hyperkalemia and hyperchloremic metabolic acidosis." (PMID 32131390, 2020). "Mutations in WNK1, WNK4, KLHL3, and CUL3 all result in the accumulation of WNK-kinase 4 and subsequent hypertension, hyperkalaemia, and metabolic acidosis." (PMID 31795491, 2019). "Akt/PKB1 activation of WNK1 in the kidney is also seen in db/db mice suggesting it has a role in the hypertension seen in the metabolic syndrome." (PMID 27815594, 2017). "Single nucleotide polymorphisms rs3754777 (STK39) and rs1468326 (WNK1) were associated with hypertension and BP in our multicenter Belgian case-control study, which supports the role of STK39 and WNK1 as potential hypertension susceptibility genes." (PMID 27082544, 2016). "We looked for an association between hypertension, BP, and genetic variants of STK39 and WNK1 in the BELHYPGEN case-control study, including predominantly severe hypertensive patients." (PMID 27082544, 2016). "Since then, a series of animal experiments and epidemiologic studies concentrated on the association between WNK1 and WNK4 gene mutations and hypertension or blood pressure regulation." (PMID 25266424, 2014). "There are four mammalian WNK family members, and positional cloning has identified two of them, WNK1 and WNK4, as genes linked to a hereditary form of human hypertension known as Pseudohypoaldosteronism type II (PHAII)." (PMID 23383144, 2013). "There are four mammalian WNK family members, and WNK1 and WNK4 genes are linked to a hereditary form of human hypertension known as Pseudohypoaldosteronism type II (PHAII)." (PMID 23383144, 2013). "Some mutations in human WNK1 or WNK4 are associated with Pseudohypoaldosteronism type II, a form of hypertension." (PMID 23383144, 2013). "It is known that genetic mutations in the kinase WNK1 and WNK4 cause a disease featuring hypertension and hyperkalemia and the etiology appears to be related to regulation of NKCC and KCC." (PMID 23537040, 2013). "We also observed higher WNK1 AluYb8 frequency among HYPEST essential hypertension patients (n = 673; 17.7%) compared to normotensive controls (n = 601; 14.5%; Supp." (PMID 21520334, 2011). "WNK1 - a serine/threonine kinase involved in electrolyte homeostasis and blood pressure (BP) control - is an excellent candidate gene for essential hypertension (EH)." (PMID 19347040, 2009). "Mutations in the WNK1 gene increase L-WNK1 expression in the distal tubule, leading to overstimulation of the WNK-SPAK/OSR1-NCC pathway, which results in enhanced NaCl reabsorption and contributes to hypertension." (PMID 39859138, 2025). "This case highlights an atypical presentation of GS in a 14-year-old boy and his father, both carrying a WNK1 gene mutation yet lacking the hallmark symptom of hypertension." (PMID 40530196, 2025). "WNK1 (Veríssimo and Jordan 2001), a widely expressed serine-threonine kinase, is known to modulate ion homeostasis, with much research focusing on its relationship with hypertension and other human diseases." (PMID 38886655, 2024). "Subjects carrying missense mutations in the WNK1 conserved acidic motif have a clear electrolyte phenotype without hypertension, especially in comparison with those who have similar nucleotide variations in a similar protein motif of WNK4." (PMID 37895227, 2023). "Patients with the reported WNK1 mutation develop hyperchloremic hyperkalemia, without arterial hypertension." (PMID 36790288, 2023).